MTOR (mechanistic target of rapamycin kinase)
Diseases named in the same sentence as MTOR in open-access papers (continued):
Sharing a sentence is not in itself a finding about the gene and the disease.
cancer (continued). "If an OS cancer stem cell exists, we suspect that mTOR and ALDH activity play pivotal roles in the maintenance of this subpopulation of cancer cells." (PMID 23476113, 2013). "Pharmacologic inhibition of c-Src as well as knockdown of its expression by shRNA showed that c-Src plays an essential role in mediating α6β4 dependent mTOR activation in MDA-MB-435/β4 and MDA-MB-231 cancer cells." (PMID 24180592, 2013). "ERK induces autophagy in neuronal cell death and cancer cells and ERK upregulates starvation-induced autophagy by down-regulating Akt/mTOR/S6K." (PMID 23894332, 2013). "In terms of pathway information which is important for understanding gene and protein function, cancer related pathways, such as MAPK signaling pathway, mTOR signaling pathway, and focal adhesion, were the most associated pathways of candidate HCC markers." (PMID 24391994, 2013). "Apoptosis is an important tumor suppressor mechanism that is blocked in the majority of human cancers, due to the over activation of the AMPK and Akt/mTOR pathway." (PMID 24359639, 2013). "HIF plays a crucial role in EMT of cancer cells and the PI3K/Akt/mTOR pathway plays a central role in this process." (PMID 23305401, 2013). "Mitochondrial function and ROS generation are involved in PI3K-Akt-mTOR and MAPK (JNK/ERK) signaling for autophagy in cancer." (PMID 23760395, 2013). "The absence of functional PTEN protein expression has been observed in various cancer cells and has led to the constitutive activation of downstream components of the PI3K pathway, including the Akt and mTOR kinases." (PMID 23509459, 2013). "Tumour angiogenesis is prevented by mTOR inhibitors through two mechanisms: i) decreased synthesis and release of angiogenic growth factors (especially VEGF) from the cancer cells and ii) blocked growth by the reduction of vascular cell survival." (PMID 24244540, 2013). "The mammalian target of rapamycin (mTOR) is a serine/threonine kinase that is often hyperactivated in cancer, and stimulation of both Akt and ERK1/2 can lead to activation of a protein complex containing mTOR, i.e., mTORC1." (PMID 22761867, 2012). "Considering the compensatory relationship between RAS/RAF/ERK and PI3K/AKT/mTOR pathways, KRAS mutant cancer cell lines have shown a synergistic effect of PI3K and MEK inhibitors." (PMID 22159814, 2012). "Subjects were recruited from 666 PCa patients and 708 cancer-free controls, and eight SNPs in the PTEN/AKT/mTOR axis were determined by the TaqMan assay." (PMID 22815832, 2012). "In total 25 genes, including the WRN progeria gene, the MYC cancer gene and the longevity MTOR (also known as FRAP1) gene, were selected for replication analyses." (PMID 22247756, 2012). "Indeed, resistance exercise in healthy conditions stimulates the Akt/mTOR signaling pathway, this being reported to be unaffected or even hyperactivated in tumor-bearing animals, suggesting the uselessness of Akt stimulation to prevent muscle wasting in cancer cachexia." (PMID 22565649, 2012). "In many cancer cells, downregulation of miR-100, miR-101 and miR-199-3p, which bind to the 3′UTR of mTOR mRNA to block its protein levels, has been shown." (PMID 22879939, 2012). "The NF1 gene is a tumor suppressor gene and multiple key pathways are potentially involved in the development of cancer in NF1 cases such as RAS/mitogen-activated protein kinase (MAPK) and AKT/mammalian target of rapamycin (mTOR)." (PMID 22236362, 2012). "Furthermore, we demonstrate that simultaneous inhibition of class I PI3K and mTOR may offer a better therapeutic approach for canine cancer therapy than the concomitant treatment of the PI3K pathway in combination with conventional cancer cytotoxic drugs." (PMID 22647622, 2012). "Antroquinonol displays anti-cancer activity against the hepato carcinoma cells through AMPK activation and inhibition of mTOR translational pathway, leading to G1 arrest of the cell-cycle and subsequent cell apoptosis." (PMID 22582152, 2012).
cancer (continued). "Nevertheless, the intersection between mTOR, insulin signaling, and AMPK provides an intriguing, tantalising link between cellular energy and cancer pathways." (PMID 22548055, 2012). "Taken together, our study has identified Akt/GSK-3β and mTOR as important targets of DHC and has thus highlighted its potential application in angiogenesis-related diseases, such as cancer." (PMID 22359572, 2012). "One of the major consequences of PTEN alteration is the activation of its main downstream targets AKT and mTOR, which are oncogenic in HNSCC tumorigenesis and are attractive targets for cancer therapies." (PMID 22666248, 2012). "In this study, it was found that luteolin supressed the activation of AKT, ERK, mTOR, P70S6K, MMP-2, and MMP-9 in a concentration-dependent manner in PC-3 cancer cells." (PMID 23300633, 2012). "PI3K/Akt/mTOR signaling pathway is overactivated in APL and AML cells and plays an important role in proliferation, drug resistance, inhibition of apoptosis in cancer cells." (PMID 23259068, 2012). "Androgen exposure upregulated pathways related to insulin, mTOR and peroxisome proliferator-activated receptor (PPAR) signaling, and downregulated those involved with the cell cycle, RNA transport and cancer." (PMID 22605918, 2012). "Although there have been many advances in our understanding of other key pathways involved in cancer such as Wnt/beta-catenin, Notch and hedgehog, we have primarily focused on the Ras/Raf/MEK/ERK and PI3K/PTEN/Akt/mTOR pathways due to space considerations." (PMID 23455493, 2012). "Recent findings suggest that eIF4E activity is a key determinant of the PI3K/Akt/mTOR and Ras/Raf/MEK/ERK mediated tumorigenic activity and targeting eIF4E should have a major impact on these pathways in human cancer." (PMID 22392765, 2012). "Several of the other genes are relevant to cancer—in addition to ERBB2, SKAP1 is an adaptor for Src, DEPTOR regulates the mTOR pathway and NRIP1 is an estrogen-receptor coregulator." (PMID 23260012, 2012). "Hence mTOR inhibitors such as rapamycin may be effective in cancer therapy." (PMID 21422497, 2011). "The mTOR inhibitors are approved for advanced RCC patients; therefore, the possibility of combing a new cancer vaccine with an established therapy that has unexpected immunostimulatory properties is attractive." (PMID 21285988, 2011). "Therefore, it may be possible to use mTOR inhibitors to enhance vaccines targeting cancers." (PMID 21285988, 2011). "Efforts to establish predictive markers to allow selection of patients with tumours likely to respond have centred on determining phosphorylation states of mTOR or its targets 4E-BP1 and S6K in cancer cells." (PMID 21320304, 2011). "In cancer cells, AMPK is reported to be a key regulator of autophagy via a mechanism that involves inactivation of mTOR and cardiac myocytes." (PMID 21386904, 2011). "For example, cancer researchers predominately consider that Raf, MEK, PI3K, Akt and mTOR inhibitors will suppress the growth of malignant cancer cells." (PMID 21422497, 2011). "The pathways associated with the largest age-related decreases in miRNA levels of BMSCs (P ≤ 0.05) included those involved in molecular mechanisms of cancer, PTEN signaling, mTOR signaling, and RAN signaling." (PMID 22169120, 2011). "Metformin's molecular targets in cancer cells (e.g., mTOR, HER2) are similar to those currently being used for directed cancer therapy." (PMID 22203527, 2011). "Understanding the immune effects of mTOR inhibition is particularly relevant for immunoresponsive diseases, such as RCC and melanoma, for which novel cancer vaccines are being actively developed." (PMID 21285988, 2011).
cancer (continued). "In this study, we examined the role of mTOR in the regulation of CD133+ CSCs differentiation, the conversion of CD133- conventional cancer cells to CD133+ CSCs, and the repopulation in vivo of mTOR-manipulated tumor cells." (PMID 22145042, 2011). "For example, cancer researchers predominantly feel that Raf, MEK, PI3K, Akt and mTOR inhibitors will suppress the growth of malignant cancer cells." (PMID 21411864, 2011). "Thus, mTOR inhibitors may play an important role in the management of cancer." (PMID 21584218, 2010). "In contrast, most compounds targeting the mTOR and IGF1R pathways equally inhibited both invasive and non-invasive spheroids, normal cells in 3D, or cancer cells in monolayer cultures." (PMID 20454659, 2010). "mTORC2 is composed of mTOR/Rictor/mLST8/SIN1/Protor/Deptor and is generally described as being insensitive to rapamycin/rapalogs, although long-term treatment of about 20% of cancer cell lines with rapamycin/rapalogs leads to dissociation of mTORC2." (PMID 20671809, 2010). "For this purpose, cancer cells were treated with CDDO-Me (0.625 to 5 μM) for 24 h and cell lysates analyzed for p-Akt, p-mTOR and NF-κB (p65) by Western blotting." (PMID 21799944, 2010). "In contrast to the EMT/mesenchymal markers, many genes downstream of AKT and related cancer-relevant pathways (PI3-Kinase, PTEN, IGF1R, mTOR and S6 Kinase) are induced when PC-3 and PC-3M cells become invasive." (PMID 20454659, 2010). "In cancer cells, inhibition of the PI3-kinase/Akt/mTOR signalling pathway, including inhibition of mTOR with rapamycin, was shown to counteract Akt-mediated resistance to drugs inhibiting tubulin and to restore apoptosis." (PMID 19127256, 2009). "The mTOR inhibition induced by AMPK is in line with the existence of a link between AMPK and the growth inhibition of some cancer cells." (PMID 19609453, 2009). "AMPK activation is a possible therapeutic target for cancers, since AMPK inhibits mTOR signalling, which in turn inhibit tumour growth in vitro and metastasis in experimental animal models." (PMID 19723334, 2009). "Based on the reported ability of mTOR to affect VEGF levels, we evaluated the effect of everolimus on VEGF production in our cancer cell lines." (PMID 18319715, 2008). "Akt/mammalian target of rapamycin (mTOR) signaling was only transiently inhibited by low doses of luteolin, which suggested that the inability to cause sustained Akt/mTOR inhibition may contribute to p21 induction and provide a survival advantage to HER2/neu-overexpressing cancer cells." (PMID 18946424, 2008). "We used everolimus (RAD001) to inhibit mTOR, alone or in combination with anti-EGFR drugs gefitinib or cetuximab, on human cancer cell lines sensitive and resistant to EGFR inhibitors, both in vitro and in vivo." (PMID 18319715, 2008). "Several inhibitors of this pathway, such as rapamycin and its derivatives which inhibit mTOR (FRAP1) and the PI3K (PIK3C2A) inhibitor wortmannin, are in fact now being actively evaluated in clinical trials for other cancers." (PMID 18538015, 2008). "In addition, mTOR targeting by the specific inhibitor everolimus not only results in significant antiproliferative activity but also restores sensitivity to anti-EGFR drugs in resistant cancer cells, producing a strong reduction of Akt activation, when used in combination with anti-EGFR drugs." (PMID 18319715, 2008). "Combined use of luteolin (5 to 10 μM) and mTOR inhibitor rapamycin (100 nM) prevented low doses of luteolin from inducing p21 expression, and HER2/neu-overexpressing cancer cells would be sensitized toward luteolin-induced apoptosis." (PMID 18946424, 2008). "Survivin is highly expressed in several cancers, and its expression is sensitive to PI3K/Akt/mTOR inhibitors." (PMID 17311107, 2007). "Thus, our results suggest that mTOR may be a likely chemotherapeutic target for cancer." (PMID 17996122, 2007).
cancer (continued). "In different cancers, activation of Akt acts by phosphorylation of transcription factors, signalling components such as IKK, caspase 9, mTor, Bad and others." (PMID 16721361, 2006). "Thus, it is possible that the mTOR pathway could control the activity of miRNAs in cancer." (PMID 16404421, 2006). "These RNA networks intersect with major oncogenic pathways, including PI3K/AKT/mTOR signaling, hypoxia responses, and epigenetic regulators such as EZH2, thereby affecting key cancer processes such as proliferation, epithelial-mesenchymal transition (EMT), and metabolic reprogramming." (PMID 42192969, 2026). "Gaining deeper insights into ATM’s relationship with mTOR and PI3K/Akt signaling pathways could support the use of pathway inhibitors in cancer therapy." (PMID 41557625, 2026). "It is important to note that mTOR inhibitors are not a one-size-fits-all solution, and their effectiveness can vary depending on the cancer's specific type and genetic characteristics." (PMID 39779613, 2025). "To model molecular interactions in sufficient complexity, we used ModCellTM, a mechanistic model based on cancer-related signaling pathways such as the Hedgehog, Wnt, RAS/MAPK, and PI3K/AKT/MTOR signaling, that either enhance MYC transcriptional activity or suppress apoptosis via effector caspases." (PMID 40968384, 2025). "mTOR-mediated cellular growth and inflammation in the kidney is one potential mechanism contributing to CKD, while mTOR also augments growth and proliferation of cancer cells." (PMID 40574888, 2025). "The most frequently investigated mechanisms included the dysregulation of the PI3K/AKT/mTOR and MAPK signaling pathways, enhanced DNA damage repair via non-homologous end joining (NHEJ), and the overexpression of cancer stem cell markers such as CD44+/CD24−/low and ALDH1." (PMID 40864743, 2025). "The epidermal growth factor receptor (EGFR) is a critical regulator of multiple oncogenic signaling cascades, including MAPK, PI3K/AKT/mTOR, and JAK-STAT pathways, which collectively contribute to enhanced proliferation, angiogenesis, and resistance to apoptosis in cancer." (PMID 41449180, 2025). "ROS further inhibited the Akt/mTOR and MAPK/ERK signaling pathways in cancer cells." (PMID 40123978, 2025). "The results demonstrated that curcumol is involved in several key signaling pathways related to sorafenib-resistant HCC, including “Pathways in cancer”, “PI3K-Akt signaling pathway”, “HIF-1 signaling pathway”, “Ras signaling pathway”, “mTOR signaling pathway”, and “JAK-STAT signaling pathway”." (PMID 40242448, 2025). "Furthermore, CX-5461 works in combination with PIM kinase, mTOR (everolimus), and histone deacetylase (panobinostat) inhibitors in MYC-driven cancer models, through amplifying the inhibition of ribosome biogenesis, protein synthesis, and metabolic homeostasis." (PMID 40805230, 2025). "Phytocompounds may target various deregulated signaling pathways, including NF-кB, PI3K/mTOR, MAPKs, AMPKs, TGF-β, Wnt/β-catenin and JNK/STAT3 pathways in various cancers." (PMID 40294146, 2025). "In cancer cachexia, PPARγ may mediate a dynamic interplay with AMPK, mTOR, and PGC-1α, orchestrating the balance between anabolic and catabolic processes." (PMID 41476922, 2025). "Moreover, the PI3K/Akt/mTOR signalling pathway, found in the rich concentration of related signalling pathways, suggested that this signalling pathway may play a role in the regulation of key enzymes of the Warburg effect, cancer stemness reprogramming factors and cancer stemness markers." (PMID 40717222, 2025).
cancer (continued). "The expression of PD-L1 in different cancers can be regulated by a number of transcriptional factors, including HIF-1, STAT3, NF-κΒ, and AP-1 and certain oncogenic pathways such as JAK/STAT, RAS/ERK, or PI3K/AKT/MTOR." (PMID 40149335, 2025). "However, when combined with baicalein, metformin significantly reduced cancer cell viability at a much lower IC50 and more effectively inhibited the AMPK/PI3K/mTOR pathway, indicating that baicalein sensitizes cancer cells to metformin’s effects." (PMID 41303544, 2025). "Studies in MPNSTs and other cancers illustrate one fundamental problem with mTOR inhibitors—they are cytostatic, not cytotoxic." (PMID 40723291, 2025). "Moreover, neutrophils have the ability to generate S100A8/9, activating the NF-κB, PI3K/AKT, mTOR and MAPK pathways that enhance cancer growth and invasion." (PMID 41429896, 2025). "Among the cancers analyzed, AML exhibited the highest activity of the PI3K/AKT/mTOR pathway." (PMID 40917720, 2025). "Related to the PI3K/mTOR signaling pathway and its value as a prognostic factor, positive expression of the AKT, mTOR, and P70S6K proteins was found in patients with advanced-stage cancer, with low differentiation and metastasis." (PMID 40804837, 2025). "Although it has been shown that plant extracts can induce apoptosis in cancer cells, the precise molecular processes at play—most notably, the role of the PI3K/AKT/mTOR signaling pathway—remain unclear." (PMID 40717210, 2025). "mTOR-mediated inflammatory responses can also promote the recruitment of immune cells to TIM, which may exert antitumor effects or contribute to cancer cell growth, progression, and metastasis." (PMID 40041495, 2025). "The mTOR inhibitors, including AZD8055, ABI‐009, CC‐223, Rapamycin, and RAD001, have been widely investigated in clinical trials and effectively applied in immunotherapy or adjuvant therapy across various cancers." (PMID 40959206, 2025). "Strategies to target cancers with ARID1A and KDM6A deficiency are not as mature as those targeting the PI3K/AKT/mTOR pathway; however, several recent promising results have been reported, offering hope for future research." (PMID 40723241, 2025). "The search terms included ‘irisin’ or ‘Fndc5’ with ‘cancer’, ‘tumour’, ‘neoplasia’, ‘oncogenesis’, ‘cell proliferation’, ‘apoptosis’, ‘metastasis’, ‘epithelial-mesenchymal transition (EMT)’, ‘IGF-1’, and ‘PI3K/Akt/mTOR pathway’." (PMID 41002741, 2025). "Furthermore, in various cancer types, including lung, breast, cervical, and prostate cancers, curcumin downregulates PKM2 through the inhibition of the mTOR/HIF-1α signaling pathway, which disrupts glucose uptake and lactate release." (PMID 41515171, 2025). "In this regard, the eukaryotic initiation factor 4F complex (eIF4F) composed of eIF4E-eIF4G-eIF4A is located at the convergence of several pathways involved in cancer, notably the PI3K/Akt/mTOR and potentially the oncogenic STAT1 that promotes the expression of B-cell lymphoma xl (Bcl-xL) gene." (PMID 40332401, 2025). "AKT-mediated phosphorylation of downstream targets, including mTOR, GSK, and NF-κB, underscores its vital roles in driving the malignant phenotypes of cancer cells by promoting cell cycle progression, inhibiting apoptosis, and enhancing metabolic reprogramming 42-44." (PMID 39744441, 2025). "Notably, many samples had co-occurring alterations in two cancer-relevant pathways, including 17.2% and 14.7% of samples with a cell cycle pathway alteration as well as a MAPK or PI3K/AKT/mTOR pathway alteration, respectively." (PMID 40711866, 2025). "Therefore, investigating a new compound that inhibits mTOR and AKT activity is crucial for cancer treatment." (PMID 40374533, 2025).